ZEB1 (zinc finger E-box binding homeobox 1)
Diseases named in the same sentence as ZEB1 in open-access papers (continued):
Sharing a sentence is not in itself a finding about the gene and the disease.
cancer (continued). "Thus, the detailed mechanisms by which ZEB1 and ZEB2 contribute to poor prognosis in cancer remain to be elucidated." (PMID 28618162, 2017). "ZEB1 is a zinc finger E-box binding transcription factor known for participating epithelial-mesenchymal transition (EMT), a critical cellular event for metastasis of malignant tumors of epithelium origin." (PMID 28246385, 2017). "The likely decision to tend toward a more cancer stem cell-like phenotype rests on ZEB1 not binding the LIF promoter." (PMID 28246407, 2017). "A mesenchymal phenotype, characterised by low expression of E-cadherin (CDH1), high expression of vimentin (VIM) and high expression of EMT-inducing transcription factors, such as TWIST1, ZEB1, SNAI1 and SNAI2 moreover correlates with the expression of cancer stem cell markers CD44 and CD90." (PMID 29299154, 2017). "Of the 40 carcinomas, negative, weakly, moderately, and strongly positive ZEB1 immunoexpressions were observed in 7 (17.5%), 14 (35.0%), 11 (27.5%), and 8 (20.0 %) patients, respectively." (PMID 29245917, 2017). "In contrast, non-cancer stem cells whose ZEB1 promoter existed in a univalent, H3K27me3 marked state were unable to activate either ZEB1 transcription or a cancer stem cell phenotype in response to TGFβ." (PMID 27528222, 2016). "DCLK1 is now suggested to be a master regulator, regulating the pluripotency factors, including Nanog, Oct4, Sox2, Klf4, and Myc, that are critical for stemness of cancer cells and EMT transcriptional factors, including Snail, Slug, Twist, and Zeb1 for metastasis and survival in many solid tumors." (PMID 27335684, 2016). "Because these processes might be selectively deregulated in cancer cells during EMT progression, ZEB1 stability and its regulators represent attractive targets for development of therapeutic interventions." (PMID 27526108, 2016). "ZEB1 downregulates E‐cadherin, decreases vascular endothelial cadherin and Flk‐1 expression, as well as induces EMT and stemness maintenance in VM‐positive cancer cells." (PMID 27027258, 2016). "As expected, in cancer cells, NKX6.3 expression regulated the expression of EMT-related proteins, such as E-cadherin, Zo-1, N-cadherin, β-catenin, Snail, Slug, Vimentin and ZEB-1." (PMID 27333045, 2016). "Both invasive and in situ carcinoma expressed less Slug and Twist and more Zeb1 compared to normal epithelium." (PMID 27429011, 2016). "Loss of expression of the miR-200 family members may play a critical role in the repression of E-cadherin by ZEB1 and ZEB2 during EMT, thereby enhancing migration and invasion during cancer progression." (PMID 27285757, 2016). "Prospective clinical studies will demonstrate whether the ‘common ZEB1/YAP target gene set' will be a useful tool to predict clinical outcome and therapy response of breast and other cancer types." (PMID 26876920, 2016). "EMT transcription factors Zeb1, Snail and Twist1 are important players in the regulation of EMT during cancer metastasis through different signaling cascades, including the Akt, Erk1/2 and signal transducer and activator of transcription 3 (STAT3) signaling pathways." (PMID 27121055, 2016). "Nevertheless, the prevalence of the ZEB1/miR-200 axis and E-cadherin in regulating EMT suggests that the Z-cad sensor provides a widely applicable tool for studying the role of EMT and MET in cancer." (PMID 27317311, 2016). "In cancer cells, EMT is a complex process, which may be regulated by multiple transcription factors such as Slug, Zeb1 and Zeb2." (PMID 26207647, 2015). "ZEB1, zinc finger transcription factor, is essential for regulating EMT and cancer metastasis." (PMID 26320193, 2015). "The zinc finger transcription factors Zeb1 and Zeb2 (also named SIP1), downstream of the Snail and Twist families in the EMT interactome, also make a pivotal contribution to this regulation in the initiation of metastasis for cancer progression." (PMID 25460509, 2015).
cancer (continued). "Therefore, existence of a feedback loop between ZEB1 and miR-141 serves to stabilize the EMT process and regulate the invasion of cancer cells." (PMID 26516699, 2015). "The high-grade budding cancer showed a nuclear translocation of β-catenin toward the invasion front, loss of membranous E-cadherin, absence of CDX2, and increased ZEB1 and ZEB2 in stromal cells at the invasion front." (PMID 25528769, 2015). "Considering the importance of Zeb1 in EMT initiation, the findings presented here have implications on our current understanding of the TGF-β signaling network, the regulation of Zeb1 and the molecular steps behind the aberrant induction of the EMT program in cancer." (PMID 25528765, 2015). "Other groups have shown that activation of ZEB1 results in the active repression of the expression of other genes, including those that are involved in cell polarity differentiation of epithelial cells and those that are involved in EMT in cancer development." (PMID 26090296, 2015). "Importantly, we were able to validate these findings using low-passage cancer cell lines (UM18 and UM59) derived from human primary PDA samples, where silencing of ATDC significantly inhibited CD44, Snail1, and Zeb1 expression." (PMID 25593307, 2015). "TWIST1 has been indicated as oncoprotein, which, with the support of other transcription factors, like SNAIL1, SLUG and ZEB1, regulates the expression of Cadherins and some other proteins involved in both of EMT and metastasis process, as well as cancer initiation and progression." (PMID 26023736, 2015). "Very importantly, a recent elegant study by Weinberg group indicates that Zeb1, a key EMT regulator, is sufficient to switch the cells from a non-cancer stem cell to a cancer stem cell status and is required for the maintenance of the stemness of breast cancer stem cells." (PMID 24618337, 2014). "Moreover, MUC1 promotes a metastatic phenotype of cancer cells by inducing EMT and activating the ZEB1/miR-200c regulatory loop." (PMID 25499743, 2014). "Loss of the expression of any members of the miR-200 family may play a critical role in the repression of CDH1 by ZEB1 and ZEB2 during the EMT, thereby enhancing migration and invasion during cancer progression." (PMID 24454732, 2014). "miR-200c,which along with miR-141 is a member of the miR-141∼200c cluster (cluster 59) as well as the miR-8 family targets the transcriptional repressor zinc-finger E-box binding homeobox 1/2 (ZEB1/2) and SIP1 is a critical inducer of EMT in several cancer types, including colorectal." (PMID 25330373, 2014). "Since the frequency of ZEB-1 expression was low, ZEB-1 expression was categorized as positive if at least 1% of cancer cells exhibited nuclear staining (n = 23; 21.3%) or as negative if very few or no cancer cells were stained (n = 85; 78.7%)." (PMID 24304617, 2013). "It has been reported that the interactions of yEF1/ZEB1 and the miRNA-200 family members miR-141 and miR-200c are part of a transcriptional feed forward loop that stabilizes epithelial mesenchymal transition (EMT) and promotes cancer invasion." (PMID 23950995, 2013). "Recently we and others have shown that this morphological plasticity of cancer cells is mediated by a double-negative feedback loop between ZEB1 and the miR-200 family members." (PMID 23667256, 2013). "In the context of gastrulation, zeb1 genes appear to contribute to fine-tuning of cell adhesion during the complex morphogenetic movements, in contrast to ZEB1 setting an EMT-like switch in cancer metastasis." (PMID 23667256, 2013). "By real-time quantitative RT-PCR, we found that ZEB1 expression levels were significantly higher in cancer tissues from patients with CRC (0.843±0.693) than in the normal adjacent mucosa (0.586±0.488; P=0.003)." (PMID 23420790, 2013). "ZEB-1 expression was classified into four groups: absent (n = 85), 1 ~ 5% of all cancer cells (n = 12), 6 ~ 10% (n = 7) and >10% (n = 4)." (PMID 24304617, 2013).
cancer (continued). "Recently, several groups showed a mutual negative feedback loop between ZEB1/2 and miRNAs of the miR200 family regulating cellular plasticity in cancer cells but also in renal tubular cell lines." (PMID 22912891, 2012). "ZEB1 (also known as δEF1, zfhx1a, TCF8, and Zfhep) plays a key role in regulating such diverse processes as T-cell development, skeletal patterning, reproduction, and cancer cell metastasis." (PMID 22190929, 2011). "Our findings may suggest that carcinoma cells in vivo, stimulated by stroma-derived TGF-β, might respond to ZEB1 inactivation with MET resulting in reduced invasiveness and CAR up-regulation, and in improved adenovirus uptake." (PMID 21791114, 2011). "As both miR-200 and ZEB1 play important roles in EMT we hypothesize that module 25 repression might contribute to the malignant EMT process in cancer cells." (PMID 20418949, 2010). "ZEB1 expression is confined to cells of mesenchymal origin, while normal epithelial cells and low grade carcinomas do not express ZEB1." (PMID 20049172, 2010). "A negative feedback loop between ZEB1 and microRNA-200 family has recently been described in various carcinoma models." (PMID 24281177, 2010). "Among these miRNAs, some are highly relevant in cancer, such as miR-205 and miR-200b, which were H3K4me3 marked in EP156T cells and H3K27me3 marked in PC3 cells, and have been reported as suppressors of the transcription factors ZEB1 and SIP1." (PMID 19262738, 2009). "Moreover, while ZEB1 was identified as a direct downstream target of miR‐143‐3p, the regulatory relationships involving ZHX3 and ZNF148 in ESCC remain to be elucidated given their structural similarity and potential roles in cancer progression." (PMID 41020579, 2025). "Although the combined activation of transforming growth factor β/WNT signaling pathways has been demonstrated to induce ZEB1-dependent repression of GRHL2 expression and EMT, surprisingly little is known about mechanisms and signaling pathways regulating GRHL2 activity in cancer cells." (PMID 40889682, 2025). "Moreover, our epithelial-to-mesenchymal transition (EMT) analysis revealed a consistent inverse association between PEBP1/STK11 co-expression and EMT marker genes, including SNAI1, SNAI2, FOXC2, ZEB1, and FN1, across most cancer types examined, thus underscoring a uniform anti-EMT signature." (PMID 40806276, 2025). "Therefore, Zeb1, along with CD44, promotes cancer cell migration." (PMID 40806166, 2025). "In LA3IK-treated samples, a significant downregulation was observed among genes central in cancer-related inflammation and epithelial-mesenchymal transition (EMT), exemplified by the reduced expression of IL1B, CXCL-8, matrix metalloproteinase 1 (MMP-1), and Zeb-1." (PMID 38272230, 2024). "In addition, exosomal ZEB1 derived from hypoxic CSCC cells promotes SIRPα+ TAM polarization via activation of the STAT3 signalling pathway and thus facilitates immune evasion by cancer cells." (PMID 38183060, 2024). "On the one hand, SARS-CoV-2 infection promotes cancer cell proliferation and stimulates the progression of the epithelial-to-mesenchymal transition (EMT) of cancer cells by upregulating Zinc-finger E-box-binding homeobox 1 (ZEB1), a well-established regulator of EMT." (PMID 38542056, 2024). "Moreover, ZEB1 and Snail are reportedly regulated by the MAPK-ERK signalling pathway in cancers." (PMID 38429738, 2024). "It has been shown that the expression of transcription factors like Snail, Twist1 and Zeb1 are increased in EMT cell, which promote cells resistant to chemotherapy, making them crucial targeting points for determining sensitivity or resistance for cancer cells to chemotherapy." (PMID 38711989, 2024). "However, how Zn2+-binding works on the pleiotropic role of ZEB1 through cancer progression has not been fully elucidated." (PMID 36910659, 2023).
cancer (continued). "Interestingly, the knockdown of cancer cell-derived immunoglobulin G (cancer-IgG) in SACC suppressed EMT by upregulating E-cadherin and downregulating ZEB1/ZEB2, suggesting that cancer-IgG could be a useful prognostic marker for this disease." (PMID 37296849, 2023). "Furthermore, miR-662 overexpression in MDA-MB-231 cells substantially increased mRNA expression levels of stemness markers involved in embryogenesis and cancer, such as NOTCH1, WNT7b, ZEB1, TCF3, and SNAI2, reinforcing the notion that miR-662 expression enhanced stem-like properties of BC cells." (PMID 37443350, 2023). "In contrast, a significant inverse correlation was found between the expression of MIR200CHG and ZEB1, a core EMT marker, consistently across 20 cancers, suggesting that the function of MIR200CHG in inhibiting the EMT pathway may represent a general mechanism to suppress cancer metastasis." (PMID 38065939, 2023). "Therefore, ZEB1 levels are indirectly affected and EMT is promoted in both types of cancer." (PMID 37924077, 2023). "However, the correlation between ZEB1 and ZEB2 in cancer is yet to be elucidated." (PMID 35723302, 2022). "Since invasive cell behaviour is a metastatic trait essential to cancer dissemination, we performed transwell cell invasion assays to further elucidate how the integration of ET-1R signaling with the YAP/ZEB1 axis may impinge in the acquisition of this aggressive feature." (PMID 35477522, 2022). "In addition, the M genes that exhibited dynamic compartment changes across the cancer cell lines were enriched in the biological process related to anatomical structure morphogenesis, including COL5A2, LOX, CDH2, ZEB1, and AXL (FDRdynamic = 1.22 × 10−8)." (PMID 35637517, 2022). "In our study, we showed that PA2G4 enhanced the migration and invasion ability of cancer cells, induced a rearrangement of F-actin and modulated the expression of EMT-related molecular markers (E-cadherin, N-cadherin, occluding, Vimentin, α-SMA and ZO-1) as well as TFs (ZEB1, ZEB2 and Snail)." (PMID 35526051, 2022). "During metastasis, cancer cells of epithelial origin often reprogram their cells to a mesenchymal type, in a process termed epithelial–mesenchymal transition (EMT) that helps to spread them to other organs, via transcriptional programming, which is regulated by TWIST1, ZEB1, SLUG, and SNAIL." (PMID 33917757, 2021). "Interestingly, ZEB1 and xCT were significantly overexpressed in GBM samples, whereas they were absent in the control brain sample, further highlighting their importance in the cancer landscape." (PMID 34885110, 2021). "Furthermore, the regulation of miR-106a and miR-591 could re-sensitize PAC-resistant cancer cells by promoting apoptosis and suppressing cell migration and proliferation by targeting BCL10, caspase-7, and zinc finger E-box binding homeobox 1 (ZEB1)." (PMID 34631583, 2021). "In addition, ZEB1, ZEB2, PTEN, and SEPT7 were regulated by the three candidate miRNAs, and many studies confirm the prominent role of these genes in several biological processes and cancer progression." (PMID 34692473, 2021). "Unlike in other types of cancers, the role of Zeb1 in HNSCC and OSCC is now receiving attention." (PMID 32728068, 2020). "In addition, years of research have adequately established the immense modulatory potential of transcription factor activity as a trigger of cancer, such as the transcription factors SNAIL1 and ZEB1, mediating the epithelial-to-mesenchymal transition-related signaling pathway." (PMID 33024415, 2020). "Zinc finger E-box-binding homeobox 1 (ZEB-1) and Zinc finger E-box-binding homeobox 2 (ZEB-2) are well-known drivers of epithelial-mesenchymal transition (EMT), which not only promote normal embryonic development but also contribute to cancer progression and metastasis." (PMID 32600257, 2020).
cancer (continued). "It should be underlined that several various signaling pathways (i.e., MAPK, PI3K/Akt signaling pathways), transcription factors (i.e.,TWIST1, Snail, Slug, ZEB1/2), and cytokines (i.e., VEGF, TGFβ) may be involved in the migration and invasiveness of cancer cells." (PMID 32260268, 2020). "Moreover, strong evidence indicates that ZEB1, but not Snail or Slug, is the master regulator of phenotypic as well as metabolic plasticity of pancreatic cells, affecting cancer cell dissemination and metastasis." (PMID 32266287, 2020). "ROS are highly expressed in LECs during the onset of diabetic cataracts stimulated by high glucose, and could induce EMT by activating several transcription factors, such as Snail, STAT3, and ZEB1, which can be activated by the Notch, G-CSF, MAPK, and PI3K/Akt signaling pathways in cancer cells." (PMID 33274006, 2020). "Notably, ZEB1 can promote cancer cells resistance towards PTX, and down-regulation of ZEB1 may be a key toward re-sensitizing cancer cells to PTX chemotherapy." (PMID 32664703, 2020). "Therefore, based on recent findings demonstrating the contribution of AGR2 to the EMT and cancer progression, in addition to in silico analysis of AGR2 promoter predicting a binding site for ZEB1, we aimed to confirm regulatory effect of ZEB1 on the expression of AGR2." (PMID 32570918, 2020). "TF ZEB1, which is an important regulator of EMT during embryonic development and cancer progression, is modified by phosphorylation to increase its transcriptional activity to downregulate the expression of TGFBR3 and integrate cytokines and growth factors in the local environment of cancer cells." (PMID 31126066, 2019). "However, not all the EMT-related chemoresistance is mediated by ZEB1, as reported that paclitaxel resistance in many cancer cells are conferred by overexpression of Twist." (PMID 31783584, 2019). "The activated TF ZEB1 could positively regulate target gene MIR27A to promote cancer cell migration and angiogenesis, and also positively regulate target gene MIR29C to promote cancer cell proliferation and migration and to suppress cancer cell apoptosis." (PMID 31126066, 2019). "The therapeutic espectrum of berberine also involved the downregulation of Snail, Slug and zinc finger E-box binding homeobox 1 (Zeb1) as well as the regulation of PI3K/Akt and retinoic acid receptor alpha and beta (RARα/RARβ) signaling, acting on the proliferation capacity of various cancer cells." (PMID 31417401, 2019). "ATM phosphorylates ZEB1 at residue S585 in response to DNA damage, which accelerates its interaction with USP7, a deubiquitinase, thus increasing the stability of ZEB1, which may contribute to radioresistance in cancer cells." (PMID 31275381, 2019). "Furthermore, we assessed the proliferation of PyMT-cancer cells in the presence of control non-conditioned medium or conditioned medium from control CAFs and ZEB1-deleted CAFs (all media were supplemented with 0.5% FBS)." (PMID 31324807, 2019). "The zinc finger E‐box‐binding homeobox 1 (ZEB1) induced the epithelial–mesenchymal transition (EMT) and altered ZEB1 expression could lead to aggressive and cancer stem cell (CSC) phenotypes in various cancers." (PMID 29754422, 2018). "However, our results above raised the possibility that Zeb1 in the context of a CD44/Zeb1 loop might be critical for CGC formation and in turn cancer cell generation." (PMID 29930325, 2018). "ZEB1 promotes the EMT process by controlling the expression of E-cadherin and may have a reciprocal regulation with Ubiquilin1 (UBQLN1) and mir-200 family in cancer progression." (PMID 28212565, 2017).